IL2 (interleukin 2)
Diseases named in the same sentence as IL2 in open-access papers (continued):
Sharing a sentence is not in itself a finding about the gene and the disease.
tuberculosis (continued). "Possible functional deficiencies of CD40L-positive / IL-2-negative T-cells as well as causative factors for the expansion of this T-cell subset (e.g. immune evasion as described for CD8+ effector T-cells in tuberculosis) will have to be elucidated." (PMID 25742660, 2015). "As in patients with active tuberculosis, repeated antigen contact was associated with a decrease in IFN-γ/IL-2 double-positive T cells, and a shift towards IFN-γ single or IL-2 single-positivity distinguish patients with reactivation from those with primary immunity, respectively." (PMID 24039703, 2013). "The best fit model found was log(P(Tuberculosis)/P(sarcoidosis)) = 1.214 + 8.884 * IL1 + 0.075 * IFN + 0.32 * IL12p70 + 0.039 * TNF − 0.097 * IL5 − 0.015 * IL8 − 0.73 * IL13 − 0.606 * IL10 − 2.404 * IL2 − 4.231 * IL4." (PMID 22815689, 2012). "The untreated tuberculosis signature was dominated by IFN-γ-only-secreting T-cells which shifted consistently in longitudinally-followed patients during treatment to a signature dominated by dual IFN-γ/IL-2-secreting T-cells in treated patients." (PMID 21179481, 2010). "Thus, a baseline cytokine signature of TNFα, IL-2, and IL-17A could serve as an accurate biomarker for the diagnosis of pediatric tuberculosis." (PMID 33936077, 2021). "Other published studies in HIV-TB coinfection have also reported that IL-2 was an important biomarker of prevalent tuberculosis in HIV infected persons." (PMID 33936077, 2021). "We performed a prospective multicentre diagnostic study to evaluate the combined interferon-γ (IFN-γ) and interleukin-2 (IL-2) release assay for detect active pulmonary tuberculosis (TB) in China." (PMID 34217302, 2021). "Peripheral blood mononuclear cells (PBMCs) were isolated from each patient and the LIOSpot® TB anti-human IL-2 ELISpot assay was performed to test their proliferative response to M. tuberculosis antigens ESAT-6, CFP-10 and Ala-DH." (PMID 29856871, 2018). "Low to no IFN-γ, IL-12, IL-2 and IL-10 successfully discriminated non-infected mice from infected mice but failed to discriminate disease status amongst supersusceptible, susceptible and resistant M.-tuberculosis-infected DO mice." (PMID 26204894, 2015). "Phosphoantigen/IL-2 administration specifically induced major expansion and pulmonary trafficking/accumulation of phosphoantigen-specific Vγ2Vδ2 T cells, significantly reduced Mtb burdens and attenuated tuberculosis lesions in lung tissues compared to saline/BSA or IL-2 controls." (PMID 23966854, 2013). "The enhanced capacity of ΔmmaA4BCG/adjuvant and BCG/adjuvant vaccine formulations to induce elevated concentrations of the TNFα/IL-2 producing central memory T cells may contribute to the increased anti-tuberculosis protection seen after immunization with these preparations." (PMID 22442674, 2012). "M. tuberculosis antigen-dependent IL-2 production has been demonstrated in patients with active TB and its serum concentrations (that are elevated in patients with active TB) return to normal with treatment." (PMID 20830287, 2010). "Logistic regression analysis of the association of a positive interleukin (IL)-2 ELISpot assay, interferon (INF)-γ ELISpot assay and tuberculin skin test with potential explanatory factors for the presence of positive results in tests for the immunodiagnosis of tuberculosis." (PMID 20652022, 2010). "We used fluorophore-labelled anti-IFN-γ and anti-IL-2 antibodies with digital overlay of spatially-mapped colour-filtered images to enumerate dual and single cytokine-secreting M. tuberculosis antigen-specific T-cells in tuberculosis patients and in latent tuberculosis infection (LTBI)." (PMID 21179481, 2010). "We report a rare case of non-articular osseous sarcoidosis with progressive pulmonary lesions and persistently normal inflammatory biomarkers (ACE, CRP, ESR, IL-2, and TNF-α) that required differentiation from metastatic bone tumors and tuberculosis." (PMID 40361953, 2025).
tuberculosis (continued). "Other studies explain the reduced CD4+T lymphocyte content and thus the reduced CD4+/CD8+ ratio by circulating soluble IL-2 (CD25) receptors in both sarcoidosis and tuberculosis." (PMID 36982159, 2023). "In the context of tuberculosis field, BCG has been demonstrated to be able to induce antigen-specific Th1-type CD4+ T cells with production of IFN-γ, IL-2 and TNF-α, which is considered to exert the protection against M.tb infection." (PMID 36387134, 2022). "Previous studies have verified some cytokine secretion profiles from CD4+ T cells in patients with tuberculosis, such as IFN-γ+, TNF-α, IL-2 and CD27." (PMID 34176483, 2021). "The importance of production activation of IL-2 and TNF-α cytokines for the formation of protective immunity against tuberculosis vaccines was noted and previously actively discussed." (PMID 31683812, 2019). "tuberculosis challenge, the vaccine stimulated the highest proportion IFN-γ+IL-2+TNF+ and CD4+IL-2+TNF+ CD4+ T cell compared with adjuvant-treated or BCG-treated mice as well as the highest proportion of vaccine-specific CD4+ T cells producing IL-17." (PMID 29263854, 2016). "Several studies have demonstrated that the IL-2 response to M. tuberculosis-specific antigens is significantly higher in active TB patients, suggesting that IL-2 could be a potential infection biomarker." (PMID 28033330, 2016). "Nevertheless the median distribution cytokine profile showed a dominance of IL-2- IFN-γ+ in tuberculosis, in comparison to a balance between IL-2+ IFN-γ-, IL-2+ IFN-γ+ and IL-2- IFN-γ+ in past tuberculosis and the highest proportion of IL-2+ IFN-γ- in LTBI." (PMID 25785445, 2015). "Previously, attenuated delNS1 influenza A vectors have been used to express either lymphocyte-stimulating cytokines such as IL-2 as immune response enhancers, or the bacterial antigen ESAT-6 to induce protective immunity against tuberculosis." (PMID 26381401, 2015). "In the present study, we found that after stimulation with M. tuberculosis antigens, NKT cells isolated from tuberculosis (TB) pleural fluid mononuclear cells (PFMCs) produced IL-21 and other cytokines including IFN-γ, TNF-α, IL-2 and IL-17." (PMID 26416419, 2015). "We have previously shown that a decrease in dual-cytokine positivity of PPD-specific T cells is observed in patients with active tuberculosis, whilst a high percentage of IFN-γ/IL-2 double-positive T cells is typical for individuals with non-active states." (PMID 24039703, 2013). "Of note, despite this uniform decrease in dual-positive T cells in patients with active tuberculosis, it was unclear, why the cytokine profile in some patients showed a shift towards IFN-γ and others rather shifted towards IL-2." (PMID 24039703, 2013). "Fractalkine, IL-17, IL-6, IL-9, MIP-1β, CRP, VEGF, and IL-5 levels in saliva and IL-6, IL-2, SAP, and SAA levels in serum were significantly higher in tuberculosis patients (P < 0.05)." (PMID 24327799, 2013). "Two recent studies have assessed IFN-γ, IL-2 and TNF-α induction after overnight stimulation of whole blood or PBMC from patients with active tuberculosis and latently infected individuals." (PMID 21423578, 2011). "In this tuberculosis contact investigation with a highly symptomatic index case we performed TST and ELISpot testing with both IFN-γ and IL2 readouts among a large group of asymptomatic close contacts." (PMID 20652022, 2010). "Notably, tuberculosis patient serum samples affected exclusively phytohemagglutinin stimulated T-cell responses and particularly activation marker as well as CD40L/IL-2 positive CD4+ T-cell subsets were decreased as compared to serum from healthy contacts." (PMID 41795482, 2026). "In the same line, it has been reported that protection against pox-virus, Leishmania major malaria, and tuberculosis may also be T-cell-mediated, with various functions such as IFN-γ, IL-2, TNF-α, and granzyme B being potentially involved." (PMID 41012118, 2025).
tuberculosis (continued). "This suggests that Mtb infection may have impacted the expression of IL-2 in IFNγ+CD3+ T cells, which could potentially compromise its anti-tuberculosis effector." (PMID 39575242, 2024). "The CD patients with MAP infection in the TU/ACU study had elevated (IFNγ), TNFα and IL-17A like tuberculosis patients, but they did not have elevated IL-2, IL-5, IL-10 and GM-CSF typically reported in tuberculosis patients." (PMID 38415011, 2024). "The combined use of BCG and M72 induced a potent anti-tuberculosis cytokine profile in cynomolgus monkeys, mainly IFN-γ, TNF-α, IL-2, and IL-6, which enabled the challenge animals to achieve long-term survival and reverse the outcome of tuberculosis progression." (PMID 37841250, 2023). "The protective efficacy of rBCG::IL-2-ESAT-6 against tuberculosis was not investigated in this study." (PMID 35632582, 2022). "Instead of constructing IL-2-producing rBCG strains, an alternative approach to enhancing Th1 skewing by BCG is to directly express IFN-γ by rBCG in an attempt to improve protection against tuberculosis." (PMID 35632582, 2022). "Still, there is yet no study to demonstrate whether the mechanisms and molecules were involved in the production of IFN-γ and interleukin 2 (IL-2) (two crucial cytokines for immune responses against TB) by activated T lymphocytes on M. tuberculosis stimulation, using any relevant biological model." (PMID 36530917, 2022). "They identified, IL-2, IL-6 and INF-γ among a few others as potential biomarker for tuberculosis." (PMID 33542363, 2021). "It is also important to note that combination of the Th1 cytokines [IFN-γ, TNF-α, IL-2 and IL-12(p70)] showed an excellent predictive power in discriminating between cultures-confirmed pulmonary-tuberculosis patients against culture-negative individuals." (PMID 31086619, 2018). "Few groups have investigated the use of IL-2 levels in BAL samples from patients with tuberculosis and their results do not argue for its use as a biomarker of tuberculosis." (PMID 29125874, 2017). "Although there is still considerable controversy over what kind of immune response is required for an effective vaccine against tuberculosis, the consensus view is that a shift towards a Th1 profile should be protective, with increased production of IFN-γ, TNF-α and IL-2." (PMID 28522873, 2017). "The data suggests that these alterations could explain the loss of a protective immune response by reducing production of proinflammatory cytokines IL-2 against M. tuberculosis to some extent, and it may also help us to figure out the mechanisms leading to T cell dysfunction in TB." (PMID 26552486, 2015). "Studies have suggested that the presence of trifunctional cells secreting IFN-γ, IL-2, and TNF-α correlates with active tuberculosis, but our data did not support this association." (PMID 23966657, 2013). "For example, a tuberculosis vaccine based on modified vaccinia virus Ankara expressing antigen 85A, and the Yellow Fever vaccine induced T cells producing combinations of IFN-γ, TNF-α, IL-2, and MIP-1β." (PMID 22412866, 2012). "We present results of a tuberculosis contact investigation with a new early-secretory-antigenic-target (ESAT)-6 and culture-filtrate-protein (CFP)-10 specific interleukin (IL)-2 ELISpot in addition to ESAT-6 and CFP-10 specific IFN-γ ELISpot and tuberculin skin testing (TST)." (PMID 20652022, 2010). "Research has extensively documented that cytokines such as IFN‐γ, IL‐2, TNF‐α, and IL‐17 play crucial roles in combating M. tuberculosis and in BCG‐induced protection against TB." (PMID 40170749, 2025). "When the secretion of IL-2 and TNF is insufficient, the immune response cannot completely eliminate M. tuberculosis but is increased with the improvement in TB after anti-TB treatment." (PMID 34074345, 2021). "Active pulmonary tuberculosis (TB) patients with the less extensive disease have a higher level of IFN-γ and IL-2 in their serum than those with more advanced disease." (PMID 34202662, 2021).
tuberculosis (continued). "In summary, we found that M. tuberculosis-specific antigens induced production of IL-21 in addition to IFN-γ, TNF-α, IL-2 and IL-17 by NKT cells in pleural fluids from TB patients." (PMID 26416419, 2015). "Thus, neither the analysis of IL-2+ nor IFN-γ+ producing cells allowed clear distinction between patients with active tuberculosis and LTBI or past tuberculosis on an individual level." (PMID 25785445, 2015). "We developed a protocol for detecting antigen-induced expression of the cytokine genes IFNG and IL2 in peripheral blood T cells stimulated ex vivo with M. tuberculosis purified protein derivative (PPD), a standard reagent used for recall responses in tuberculosis." (PMID 26658491, 2015). "In contrast to the CD4+ effector functional subsets, CD4+ IL-2-only PPD- and RD1-peptide-specific cells (data not shown) were principally TCM in both active tuberculosis and latent tuberculosis infection and were therefore unaffected by tuberculosis disease stage." (PMID 23966657, 2013). "In contrast, long-lived central memory T-cells may persist even after successful treatment of tuberculosis and are less likely to release IFN-γ after short incubation with antigen while they are more likely to produce IL-2 upon antigen exposure than effector cells." (PMID 20652022, 2010). "We excluded 2,726 records for the following reasons: ineligible interventions (IL-2, HIV vaccine, etc.), ineligible individual selection (tuberculosis, monkeypox, etc.), reviews, abstracts, non-clinical trials, and non-English articles." (PMID 41327829, 2025). "Our data showed that mycobacterium tuberculosis (Mtb)-specific IFN-γ, TNF-α, IL-2, IL-6, IL-10, IL-5, IP-10, IL-1Ra, CXCL-1 and MCP-1 responses based on QFT-Plus significantly differed between Mtb-infected (including ATB, LTBI and previous TB) and uninfected healthy populations." (PMID 38166667, 2024). "In non-active or successfully treated TB patients, an elevated IL-2 response may be a consequence of the expansion of central memory T-cells, caused by a reduction of M. tuberculosis antigen loads." (PMID 28033330, 2016). "Assessment of subpopulations of IL-2+ single, IL-2+ IFN-γ+ double, or IFN-γ+ single secreting cells in the FluoroSpot did not improve the differentiation between tuberculosis, past tuberculosis and LTBI." (PMID 25785445, 2015). "In fact, our preliminary data indicate that detection of IL-2 in IFN-γ positive subjects, after stimulation with M. tuberculosis antigens, may discriminate individuals with latent infection from patients affected by active TB." (PMID 19549330, 2009). "However, in contrast to tuberculosis patients, the CD patients in the TU/ACU study did not have statistically significant increased IL-2, IL-5, IL-10, and GM-CSF." (PMID 38415011, 2024). "We analyzed frequencies of antigen-specific CD4 and CD8 T cells expressing IFNγ, IL-2, TNF and/or IL-17 from adolescents or adults, with or without Mycobacterium tuberculosis (M. tb) infection, who received MVA85A, AERAS-402, H1:IC31, H56:IC31, M72/AS01E, ID93+GLA-SE or BCG." (PMID 30830940, 2019). "Induction of IL-2, IL-6, IL-10 (not shown), IL-17A, IFN-g and was higher in participants with BCG scars, but only IL-6 were induced more in participants with no past history of tuberculosis." (PMID 29680481, 2018).
rheumatoid arthritis (86 papers, 2008 to 2025). A chronic, systemic autoimmune disorder characterized by inflammation in the synovial membranes and articular surfaces. "The ME/CFS network shows substantial overlap with pathways implicated in multiple sclerosis, rheumatoid arthritis and other chronic inflammatory disorders (shared nodes: IL-2, IL-10, CD4-T cell markers)." (PMID 41057909, 2025). "A study showed that a 480 kb block on chromosome 4q27 encompassing the KIAA1109/Tenr/IL-2/IL-21 gene cluster is associated with rheumatoid arthritis." (PMID 37667381, 2023). "Using a family-based study, we have provided a trend for the association of the KIAA1109/Tenr/IL2/IL21 gene region with rheumatoid arthritis in populations of European descent." (PMID 19302705, 2009). "A candidate gene approach, in a large case–control association study in the Dutch population, has shown that a 480 kb block on chromosome 4q27 encompassing KIAA1109/Tenr/IL2/IL21 genes is associated with rheumatoid arthritis." (PMID 19302705, 2009). "IL-2 levels in this post-CHIKV arthritis cohort were low in comparison to healthy adults and rheumatoid arthritis, which is also associated with deficient IL-2 production." (PMID 38507338, 2024). "Low dose IL-2 supplementation has been shown to achieve clinical efficacy in rheumatoid arthritis, lupus erythematosus and other auto-immune diseases." (PMID 38390873, 2024). "NK CD56brightCD16− NK cells have been found in vivo at increased proportions during IL-2 therapy, in affected tissues by pathological inflammatory conditions like rheumatoid arthritis and ex vivo IL-2-expanded primary NK cells." (PMID 31143782, 2019). "Rheumatoid arthritis was identified as the highest scored related disease based on functional analysis, and the enriched pathways were the IL-2 signaling pathway, SMAD signaling network, and MAPK signaling pathway." (PMID 29577053, 2018). "Recently, we reported a relationship of rheumatoid arthritis (RA) activity/progression with irreversible systemic Treg and Th1 defects including serum IL-2 shortage." (PMID 25145773, 2015). "A well-established rheumatoid arthritis susceptibility variant near CTLA4 decreases CTLA4 levels in T cells; here, we identify how this reduced immune checkpoint function is associated with increased levels of IL-2-producing CD8+ T cells." (PMID 30332657, 2018). "Moreover, the KIAA1109/Tenr/IL2/IL21 locus was also earlier associated with another immunological disorder, namely rheumatoid arthritis." (PMID 26941931, 2015). "IL-2 is an important stimulator and modulator of T-cell activation, adopting a key role in the pathophysiology of various immune-mediated diseases such as rheumatoid arthritis, multiple sclerosis and transplant rejection." (PMID 26049074, 2015). "It is found that low doses of IL-2 combined with tocilizumab are safe and effective in rheumatoid arthritis (RA) patients." (PMID 40337274, 2025). "Hence, QLY’s inhibition of IL-1β, IL-6, TNF-α, IL-2 and IFN-γ levels on AA rat serum might be part of the underlying mechanisms for QLY’s anti-rheumatoid arthritis effects." (PMID 34693865, 2021). "Several autoimmune diseases, including rheumatoid arthritis (RA) and psoriasis, had been considered to be Th1-cell-mediated disorders driven by a population of T cells producing inflammatory cytokines, such as IL-2, IL-12, TNF-α and interferons." (PMID 22359594, 2012). "A study on rheumatoid arthritis showed that high-dose silibinin significantly reduced inflammatory markers (ESR, IL-8, IL-6, TNF-α, anti-CCP) and increased Hb, IL-10, and IL-2, compared to placebo." (PMID 39850538, 2025). "In patients with rheumatoid arthritis, rituximab significantly reduced serum concentrations of CRP, RF, anti-CCP, IL-2, IL-6, IL-7, IL-10, and ESR." (PMID 41057909, 2025). "In the development of rheumatoid arthritis (RA), TNF-α, IL-1, IL-6, IL-2 and many other inflammatory factors mediate the inflammatory response." (PMID 38629066, 2024).